KLF17 (KLF transcription factor 17)
Description:
Transcription repressor that binds to the promoter of target genes and prevents their expression. Acts as a negative regulator of epithelial-mesenchymal transition and metastasis in breast cancer. Specifically binds the 5'-CACCC-3' sequence in the promoter of ID1, a key metastasis regulator in breast cancer, and repress its expression. May be a germ cell-specific transcription factor that plays important roles in spermatid differentiation and oocyte development (By similarity).
Synonyms: ZNF393; Zfp393; FLJ40160; ZLF393
Tractability: No criterion of Open Targets' tractability assessment is met for any kind of drug.
Gene: Protein-coding gene on chromosome 1 (44,118,821 to 44,135,140, forward strand). Ensembl gene ENSG00000171872.
Subcellular location: Nucleus
Gene Ontology:
Molecular function: protein binding; sequence-specific double-stranded DNA binding; DNA-binding transcription factor activity; DNA-binding transcription factor activity, RNA polymerase II-specific; RNA polymerase II cis-regulatory region sequence-specific DNA binding; transcription cis-regulatory region binding
Biological process: regulation of transcription by RNA polymerase II
Cellular component: chromatin; nucleus
Genetic constraint (gnomAD): Loss-of-function variants: 31 observed, 34.23 expected, observed/expected ratio (o/e) 0.91, 90% interval 0.68 to 1.22. The upper end of that interval is the gene's LOEUF score, 1.22, which puts it in group 5 of 6, group 1 being the genes least tolerant of losing a copy. Missense variants: 478 observed, 514.11 expected, observed/expected ratio (o/e) 0.93, 90% interval 0.86 to 1. Synonymous variants: 179 observed, 189.73 expected, observed/expected ratio (o/e) 0.94, 90% interval 0.83 to 1.07.
Homologues: Orthologues: chimpanzee KLF17 (98% identical), macaque KLF17 (90% identical), dog KLF17 (63% identical), pig KLF17 (58% identical), rat Klf17 (44% identical), mouse Klf17 (41% identical), dog KLF18 (22% identical), Caenorhabditis elegans klf-1 (21% identical), zebrafish klf2b (21% identical), zebrafish klf2a (20% identical), tropical clawed frog klf2 (19% identical), tropical clawed frog znf534 (19% identical), and 13 more. Paralogues in human: SP8 (21% identical), KLF2 (20% identical), KLF5 (20% identical), KLF15 (20% identical), KLF11 (19% identical), KLF3 (19% identical), KLF12 (19% identical), KLF8 (19% identical), KLF1 (19% identical), KLF4 (19% identical), KLF10 (18% identical), SP9 (18% identical), and 10 more.
Diseases named in the same sentence as KLF17 in open-access papers:
KLF17 is named in the same sentence as 31 diseases in open-access papers, as found by Europe PMC text mining. Sharing a sentence is not in itself a finding about the gene and the disease. The quoted sentences say what the papers report.
breast carcinoma (10 papers, 2011 to 2024). "The authors further identified inhibitor-of-differentiation protein ID1 as a pro-metastatic regulator downstream of KLF17, which becomes expressed in breast cancers due to loss of its repressor." (PMID 24429391, 2014). "Id1 has previously been implicated with EMT both directly, through suppression of E-cadherin and zonula occludins-1 (ZO-1), in human kidney cells and indirectly, through loss of Krueppel-like factor 17 (KLF17) in breast cancer cells." (PMID 21955753, 2011). "KLF17 inhibits epithelial-mesenchymal transition (EMT) and invasion of breast cancer cells, and KLF17 protein directly inhibits the transcription of Id1, the key regulator of the metastasis of breast cancer." (PMID 28454121, 2017). "KLF17 can suppress the invasiveness of breast cancer cells, hepatocellular carcinoma, and esophageal carcinoma and has been correlated with prognosis in these patients." (PMID 28454121, 2017). "After the knockdown of the expression of KLF17, breast cancer cells displayed the major characteristics of EMT." (PMID 26662959, 2016). "It is demonstrated that KLF17 is frequently downexpressed in the majority of human cancers, including breast cancer, lung adenocarcinoma, hepatocellular carcinoma (HCC), gastric cancer, papillary thyroid carcinoma (PTC), and non-small cell lung cancer (NSCLC)." (PMID 26662959, 2016). "KLF17 can inhibit the transcription of ID1, which is the gene of encoding a key metastasis regulator in breast cancer, via directly binding to its promoter region." (PMID 26662959, 2016). "Only two reports have shown that DJ-1 could promote EMT in breast cancer cells and human proximal tubular epithelial cells via repressing KLF17 expression or PTEN expression." (PMID 32366371, 2020). "Id1 has been reported as a negatively regulated gene by KLF17 in breast cancer." (PMID 28454121, 2017). "The anti-invasion role of KLF17 has been reported to regulate Id1 expression in breast cancer." (PMID 28454121, 2017). "Low expression of KLF17 is also an independent predictor of lymph node metastasis in breast cancer." (PMID 26662959, 2016). "Taken together, DJ-1 could promote the invasion of breast cancer cells via regulating the KLF17/ID1 pathway." (PMID 26662959, 2016). "Patients with breast cancer who had lymph node metastases typically contained a high expression level of ID1 and low levels of KLF17." (PMID 38195969, 2024). "In breast cancer, KLF17 was identified as a metastasis suppressor, counteracting EMT in the 168FARN murine breast cancer cell line, normal murine (nMuMG) and human (HMLE) breast epithelium." (PMID 24429391, 2014).
gastric cancer (4 papers, 2016 to 2025). A primary or metastatic malignant neoplasm involving the stomach. "Low KLF17 expression is significantly associated with metastasis in lung adenocarcinoma, gastric cancer, PTC, and NSCLC." (PMID 26662959, 2016). "KLF17 is poorly expressed in GCSCs, and its overexpression reportedly inhibits epithelial‒mesenchymal transition in gastric cancer cells through the TGF-β/Smad pathway, thereby reducing the invasion and migration of these cells." (PMID 40866457, 2025). "Some evidence now supports a relationship between the expression of KLF17 and poor survival in human lung adenocarcinoma, hepatocellular carcinoma, gastric cancer, and papillary thyroid carcinoma." (PMID 32019121, 2020). "Gastric cancer studies showed that the reduced expression of KLF17 protein is correlated with its lymphovascular invasion." (PMID 26662959, 2016). "Low KLF17 expression is observed in most human cancers, including colorectal carcinoma, esophageal carcinoma, hepatocellular carcinoma, lung adenocarcinoma, and gastric cancer." (PMID 32019121, 2020). "Reduced expression of KLF17 has been strongly correlated with tumor size, pathological N stage, and lymphovascular invasion in gastric cancer and is also an independent predictor of poor survival in patients undergoing gastric cancer surgery." (PMID 32019121, 2020).
liver cancer (4 papers, 2015 to 2022). An epithelial or non-epithelial malignant neoplasm that arises from the liver. "Another report, which focuses on liver cancer metastasis, reveals a positive feedback loop between Kruppel-like-factor 17 (KLF17) and TGF-β/Smad3 to prevent HCC progression and metastasis." (PMID 35409139, 2022). "In contrast, overexpression of KLF17 enhanced apoptotic level in HepG2 liver cancer cells." (PMID 25766320, 2015).
lung carcinoma (4 papers, 2015 to 2024). "In this paper, KLFs have been summarized via systematic reviews, with either a promoting (KLF4 ∼ KLF8, KLF15) or an inhibiting (KLF2 ∼ KLF6, KLK9 ∼ KLF12 and KLF17) roles, which should be useful to monitor lung cancer progression or understand its mechanisms." (PMID 38560274, 2024). "The overexpression of KLF17 also inhibits the in vitro growth of the A549 and PC-9 lung cancer cell lines, suggesting a potential role for KLF17 in suppressing tumor growth in lung adenocarcinoma." (PMID 32019121, 2020). "The results illustrated that the patients with reduced expression of KLF17 and increased expression of uPA in lung cancer were more likely to have lymph node metastasis." (PMID 28454121, 2017). "Krüppel-like factor 17 (KLF17) has been reported to be involved in invasion and metastasis suppression in lung cancer, but the molecular mechanisms underlying the anti-invasion and anti-metastasis roles of KLF17 in lung cancer are not fully illustrated." (PMID 28454121, 2017).
lung adenocarcinoma (3 papers, 2016 to 2020). A carcinoma that arises from the lung and is characterized by the presence of malignant glandular epithelial cells. "Clinical studies have shown an association between low KLF17 expression and shorter survival time in patients with lung adenocarcinoma and KLF17 expression is significantly associated with tumor stage and size." (PMID 32019121, 2020). "Reduced expression of KLF17 and overexpression of uPA were associated with a short survival time in patients with lung adenocarcinoma." (PMID 28454121, 2017). "The clinical studies showed that low KLF17 is associated with a reduced survival time in lung adenocarcinoma patients, and the distant tumor metastasis is significantly increased." (PMID 26662959, 2016). "In vitro analysis indicated that KLF17 inhibited the invasion of lung adenocarcinoma cells at least partially through the suppression of uPA." (PMID 28454121, 2017). "We then evaluated the correlation between the expression of KLF17 and uPA in tumor tissues from 43 cases of lung adenocarcinoma by immunohistochemical staining and analyzed the expression statuses of KLF17 and uPA in N stage." (PMID 28454121, 2017). "In the present study, we found that KLF17 suppressed lung adenocarcinoma cell invasion partially by negatively regulating uPA." (PMID 28454121, 2017). "Our study provides a new model for the negative regulation of uPA by KLF17 in mediating the invasion of lung adenocarcinoma via the SRC/P38/MAPK pathway." (PMID 28454121, 2017). "First, we calculated the optimal cut-off value for the immunostaining score by analyzing the correlation between KLF17 or uPA expression and the survival time of the patients with lung adenocarcinoma." (PMID 28454121, 2017). "KLF17 protein expression was negatively correlated with uPA protein expression in tumor tissues from 16 cases of lung adenocarcinoma with lymph node metastasis (rho = −0.62, P = 0.01)." (PMID 28454121, 2017). "In conclusion, our study demonstrated that KLF17 inhibited the invasion of lung adenocarcinoma cells, and the effects were correlated with the suppression of uPA expression." (PMID 28454121, 2017). "ROC curve analysis showed that the mutual and exclusive KLF17 expression with uPA is predictive for lymph node metastasis in patients with lung adenocarcinoma (AUC = 0.758, P = 0.005)." (PMID 28454121, 2017). "In conclusion, our study indicated that KLF17 suppressed the uPA-mediated invasion of lung adenocarcinoma." (PMID 28454121, 2017). "Immunohistochemical staining also showed that reduced expression of KLF17 and overexpression of uPA were both correlated with poor prognosis in patients with lung adenocarcinoma." (PMID 28454121, 2017). "Ectopic upregulation of uPA impaired the anti-invasion activity of KLF17 in lung adenocarcinoma cells." (PMID 28454121, 2017). "IHC analysis also showed that KLF17 was negatively correlated with uPA expression in patients with lymph node metastasis of lung adenocarcinoma." (PMID 28454121, 2017). "The invasiveness of A549 and H322 cells infected with pLenti-KLF17shRNA was increased significantly compared to the cells infected with pLenti-HK shRNA (P < 0.05), indicating that KLF17 suppressed the invasion of lung adenocarcinoma cells." (PMID 28454121, 2017). "KLF17 expression level is an independent prognostic indicator, and it is correlated with the tumor stage and size in lung adenocarcinoma and HCC." (PMID 26662959, 2016). "The expression level of KLF17 in lung adenocarcinoma cells and primary tumor tissues was lower than in immortal human bronchial epithelial cells and tumor-adjacent lung tissues, respectively." (PMID 26662959, 2016). "In conclusion, KLF17 might be a potential anti-invasion candidate in the treatment of lung adenocarcinoma." (PMID 28454121, 2017).
lung adenocarcinoma (continued). "The Src and p38/MAPK signaling pathways were suggested as mediators of KLF17-induced uPA inhibition, thus providing evidence that KLF17 might be a potential anti-invasion candidate for lung adenocarcinoma." (PMID 28454121, 2017). "In addition, immunohistochemistry staining showed that the protein expression of KLF17 was negatively correlated with that of uPA in archived samples from patients with lymph node metastasis of lung adenocarcinoma (rho = −0.62, P = 0.01)." (PMID 28454121, 2017). "The mutually exclusive expression of KLF17 with uPA could predict lymph node metastasis for lung adenocarcinoma (AUC = 0.758, P = 0.005)." (PMID 28454121, 2017). "In lung adenocarcinoma, low expression of KLF17 is also related to tumor growth and poor prognosis." (PMID 26662959, 2016). "In addition, increased expression of uPA and reduced expression of KLF17 were prognostic indicators for survival time of patients with lung adenocarcinoma, and KLF17 was negatively correlated with uPA expression in the tumor tissues from patients with lymph node metastasis of lung adenocarcinoma." (PMID 28454121, 2017). "The results from the immunohistochemical staining analysis showed that the expression of KLF17 was not negatively correlated with uPA expression in lung adenocarcinoma tissues unless the patients had lymph node metastasis." (PMID 28454121, 2017).
lymph node metastases (3 papers, 2016 to 2024). "Furthermore, Spearman analysis uncovered that the expression of KLF17 was negatively correlated with that of uPA only in the lymph node metastasis positive groups (rho = −0.62, P = 0.01)." (PMID 28454121, 2017).
prostate carcinoma (3 papers, 2008 to 2021). A carcinoma that arises from epithelial cells of the prostate gland. "Moreover, migration and invasion inhibitory protein (MIIP) inhibits cell invasion and epithelial–mesenchymal transition in prostate cancer through miR-181a/b-5p-KLF17 axis." (PMID 33648424, 2021).
Cirrhosis (1 paper, 2015). A chronic disorder of the liver in which liver tissue becomes scarred and is partially replaced by regenerative nodules and fibrotic tissue resulting in loss of liver function. "Results from GSE6764 data set showed that KLF17 is significantly downregulated during cirrhosis and HCC progression." (PMID 25766320, 2015).
cleft lip (1 paper, 2024). Congenital defect in the upper lip where the maxillary prominence fails to merge with the merged medial nasal prominences. "In conclusion, this review indicated the critical role of the IRF6 gene and its downstream genes (GRHL3, KLF17, and ESRP1/2) in the development of cleft lip and palate in zebrafish models." (PMID 38533046, 2024). "Taken together, our systematic review indicated the critical role of the IRF6 gene and its downstream genes (GRHL3, KLF17, and ESRP1/2) in the development of cleft lip and palate in zebrafish models." (PMID 38533046, 2024).
endometrial cancer (1 paper, 2015). Primary or metastatic malignant neoplasm involving the endometrium (mucous membrane that lines the endometrial cavity). "It has been shown that the expression of transcription factor Kruppel-like factor 17 (KLF17) induces the expression of Twist in endometrial cancer cells." (PMID 26356073, 2015). "Both Twist and KLF17 are upregulated in endometrial cancer cells." (PMID 26356073, 2015).
gastric adenocarcinoma (1 paper, 2016). "It has been identified that reduced expression of KLF17 is strongly associated with tumor size, pN stage, and lymphovascular invasion in gastric adenocarcinoma." (PMID 26662959, 2016). "Peng and colleagues reported that the expression level of KLF17 was significantly decreased in 98 of 158 gastric adenocarcinoma cases." (PMID 26662959, 2016). "Moreover, KLF17 expression is an independent prognostic factor for both overall survival and disease-free survival in gastric adenocarcinoma." (PMID 26662959, 2016).
orofacial clefting (1 paper, 2020). "Already, the human orthologs of four known elements of this GRN, Irf6, Grhl3, Klf17, and simple epithelium keratins, are implicated in risk for non-syndromic orofacial clefting." (PMID 32031521, 2020).
preeclampsia (1 paper, 2023). Preeclampsia is a hypertensive disorder of pregnancy that is characterized by new-onset hypertension with proteinuria presenting after 20 weeks of gestation, and depending on mild or severe forms may initially present with severe headache, visual disturbances, and hyperreflexia. "As in ANP and Corin KO mice, a preeclampsia-like phenotype was observed in Klf17 KO mice, including late gestational hypertension, renal ischemia, and proteinuria." (PMID 37569683, 2023).
schwannoma (1 paper, 2025). A benign, usually encapsulated slow growing tumor composed of Schwann cells. "We present a case of a 51-year-old male with a pseudoglandular cellular schwannoma arising from the brachial plexus, which contains the expected molecular aberrations for a schwannoma (chromosome 22q loss encompassing the NF2 and LZTR1 genes) as well as a FUS::KLF17 rearrangement." (PMID 40878925, 2025).